RNU6-725P (RNA, U6 small nuclear 725, pseudogene)
Gene: Small nuclear RNA gene on chromosome 1 (238,325,687 to 238,325,788, reverse strand). Ensembl gene ENSG00000252371.
Homologues: Orthologues: chimpanzee U6 (99% identical), macaque U6 (86% identical), mouse Gm25578 (71% identical), rabbit U6 (66% identical), rat LOC120099418 (65% identical). Paralogues in human: RNU6-1150P (92% identical), RNU6-338P (75% identical), RNU6-641P (75% identical), RNU6-1124P (74% identical), RNU6-435P (74% identical), RNU6-854P (74% identical), RNU6-1011P (73% identical), RNU6-1099P (73% identical), RNU6-1158P (73% identical), RNU6-1316P (73% identical), RNU6-1336P (73% identical), RNU6-166P (73% identical), and 1284 more.